BAP1 (BRCA1 associated deubiquitinase 1)
Diseases named in the same sentence as BAP1 in open-access papers (continued):
Sharing a sentence is not in itself a finding about the gene and the disease.
meningeal melanoma (2 papers, 2022 to 2024). "The presence of SF3B1–, EIF1AX–, or BAP1–mutation or complex copy number variations indicate aggressive behavior consistent with meningeal melanoma." (PMID 36497333, 2022). "Furthermore, some additional molecular alterations, such as SF3B1, EIF1AX, and BAP1 mutations, confer a significant aggressive course in meningeal melanoma, while both primary diffuse leptomeningeal melanocytosis or melanomatosis are often NRAS mutated and rarely BRAF mutated." (PMID 39061148, 2024).
metastasis (2 papers, 2021 to 2025). The spread or migration of cancer cells from one part of the body (where they first appeared) to another. "The primary tumor in their study was BAP1 IHC positive, the first bone metastasis (synchronous) was IHC negative, and the second bone metastasis (diagnosed approximately 9 months later) was BAP1 IHC positive." (PMID 34885018, 2021).
multiple myeloma (2 papers, 2018 to 2024). "We identified compounds that could selectively inhibit BAP1 deubiquitinase activity using an enzymatic activity assay approach, then demonstrated preclinical antitumor efficacy of BAP1 inhibition using these compounds in cell line and xenograft models of myeloma with ASXL1 frameshift mutations." (PMID 39403928, 2024).
pancreatic adenocarcinoma (2 papers, 2016 to 2021). "Therefore BAP1 inactivation is unlikely to be a frequent driver abnormality in pancreatic adenocarcinoma." (PMID 26982343, 2016).
pancreatitis (2 papers, 2020 to 2022). Inflammation of the pancreas. "Deletion or heterozygous loss of Bap1 in murine pancreata causes genomic instability, tissue damage, and pancreatitis with full penetrance." (PMID 32541668, 2020). "We reasoned that BAP1 ablation might trigger chronic tissue damage and pancreatitis due to defective DDR." (PMID 32541668, 2020).
prostate tumor (2 papers, 2019). "One study reported lack of BAP1 mutations in 45 prostate tumors, but data on BAP1 protein expression or its prognostic significance in this disease are currently acking." (PMID 31903168, 2019).
Sepsis (2 papers, 2025). Sepsis is defined as life-threatening organ dysfunction caused by a dysregulated host response to infection. "The deubiquitinating enzymes breast cancer susceptibility protein 1 (BRCA1)-associated protein 1 (BAP1) and USP9x are also involved in sepsis-induced AKI through the NF-κB signaling pathway." (PMID 40225869, 2025).
thyroid (2 papers, 2020 to 2025). "The significant rarity of thyroid SCC and a surprisingly high prevalence of Chr 3p LOH in DTC (40% of PTC and 67% of FTC) nonetheless predicts that pathogenic BAP1 mutations must be rare events in thyroid malignancy." (PMID 40600748, 2025).
acute pancreatitis (1 paper, 2020). An acute inflammatory process that leads to necrosis of the pancreatic parenchyma. "At the molecular level, meta-analysis of gene expression profiles of acute pancreatitis in caerulein-treated mice revealed that Bap1 and other DNA repair genes (Brca1/2 and Atm) are upregulated within hours in response to tissue damage." (PMID 32541668, 2020).
anaplastic meningioma (1 paper, 2023). A WHO grade III meningioma characterized by the presence of malignant morphologic features, including malignant cytology and a very high mitotic index (20 or more mitoses per ten high power fields). "Additionally patient #2 suffered from anaplastic meningioma CNS WHO grade 3 with BAP1 mutation, FANCC mutation and homozygous CDKN2A/B deletion in both manifestations." (PMID 36641486, 2023).
anemia (1 paper, 2023). A reduction in the number of red blood cells, the amount of hemoglobin, and/or the volume of packed red blood cells. "Germline variants of DNA repair genes including in addition to BAP1 several members of the Fanconia anemia complementation group (FANC) family as well as MSH3 have been reported in PM." (PMID 36683050, 2023).
angiomyolipoma (1 paper, 2021). A neoplasm with perivascular epithelioid cell differentiation often associated with tuberous sclerosis. "Herein, we found that the prevalence of BAP1, FLCN, and MITF p.E318K alterations in this cohort was 6.2% (5 of 81 patients, after excluding benign renal neoplasia, such as oncocytoma and angiomyolipoma; 95% CI 2.3%-14.5%) (eFigure in the Supplement)." (PMID 34767027, 2021). "Likely germline alterations of BAP1, FLCN, and MITF were identified in 6.2% of cases after excluding benign renal neoplasia (oncocytoma and angiomyolipoma)." (PMID 34767027, 2021). "Moreover, we found that the prevalence of BAP1, FLCN, and MITF p.E318K alterations in this cohort was 6.2% (5 of 81 patients, after excluding benign renal neoplasia, such as oncocytoma and angiomyolipoma; 95% CI 2.3%-14.5%)." (PMID 34767027, 2021).
angiosarcoma (1 paper, 2024). A malignant tumor arising from the endothelial cells of the blood vessels. "Splenectomy in an individual with suspected splenic angiosarcoma showed a benign vascular neoplasm with loss of nuclear staining for BAP1 in a subset of cells." (PMID 38824259, 2024). "Notably, in our clinical practice, we observed an individual with BAP1-TPDS with a suspected splenic angiosarcoma on imaging, which on splenectomy showed a benign vascular neoplasm with loss of nuclear BAP1 staining in a subpopulation of lesional cells." (PMID 38824259, 2024).
bone cancer (1 paper, 2012). A primary or metastatic malignant neoplasm affecting the bone or articular cartilage. "BAP1 carriers also reported additional kidney, bladder, uterine, breast and bone cancers though these could not be confirmed by pathology since the probands were deceased." (PMID 22545102, 2012).
chordoma (1 paper, 2024). Chordomas are rare malignant tumors arising from embryonic remnants of the notochord in axial skeleton. "The last patient to have a significant pathogenic finding was a 46-year-old female with a sacral conventional chordoma and a BAP1 deleterious mutation (c.1975A > T;p.K659Ter)." (PMID 38700789, 2024).
clear-cell carcinoma (1 paper, 2021). "Loss of 3p in clear-cell carcinoma targets driver genes of VHL, PBRM1, SETD2 and BAP1 with collateral deletion of a series passenger genes, amongst which certain genes harbor indispensable functions to maintain cancer cell viability." (PMID 34593007, 2021).
craniopharyngioma (1 paper, 2026). A benign, partly cystic, epithelial tumor of the sellar region, presumably derived from Rathke pouch epithelium.
cyst (1 paper, 2024). A sac-like closed membranous structure that may be empty or contain fluid or amorphous material. "In congruence with the reported literature, the histology of our patient’s lesions showed mesothelial lined cyst, as well as focal areas with adenomatoid proliferation in the stroma with cyst lining cells positive BAP-1 expression." (PMID 38899248, 2024).
DNA repair disorders (1 paper, 2025). "Finally, exploring other therapies with activity against DNA repair disorders, such as ATR inhibitors, or even immunotherapy combinations with novel targets, could identify personalized treatment options for patients with BAP1 loss." (PMID 40361508, 2025).
esophageal squamous cell carcinoma (1 paper, 2021). Esophageal squamous cell carcinoma (ESCC) is a type of esophageal carcinoma (EC) that can affect any part of the esophagus, but is usually located in the upper or middle third. "In this study, we aimed to explore the function of BAP1 in the pathogenesis of esophageal squamous cell carcinoma." (PMID 33529461, 2021).
familial Mediterranean fever (1 paper, 2024). Familial Mediterranean fever (FMF) is an autoinflammatory disorder characterized by recurrent short episodes of fever and serositis resulting in pain in the abdomen, chest, joints and muscles. "Other risk factors include familial Mediterranean fever, mutations involving BRCA1-associated protein 1 (BAP1), chronic peritonitis, radiation exposure, and simian viruses." (PMID 39735025, 2024).
Granuloma (1 paper, 2024). A compact, organized collection of mature mononuclear phagocytes, which may be but is not necessarily accompanied by accessory features such as necrosis. "Our study involving individuals with BAP1-TPDS noted a diverse spectrum of splenic lesions, including cysts/hemangiomas, hamartomas, and granulomas." (PMID 38824259, 2024).
hemorrhage (1 paper, 2025). Loss of blood from the vascular compartment to the exterior or into nonvascular body space as a result of rupture or severance of the blood vessels. "- SPOT Immunoblotting: to map epitopes in Atr-I, Bap1, and Leuc-a.- ELISA: to monitor antibody production against synthetic peptides- In vitro neutralization Assay: to test neutralizing activity of antibodies.- In vivo hemorrhagic Assay: to test neutralization of Atr-I-induced hemorrhage." (PMID 41043030, 2025).
Hyperglycemia (1 paper, 2025). An increased concentration of glucose in the blood. "Hyperglycemia also resulted in a minor decrease in nuclear BAP1 immunoreactivity in the 92.1 and OMM2.5 cells under interphase, with an average reduction by 16% to 18% in the integrated density and mean intensity, respectively, of both cell lines, which failed to reach significance." (PMID 41328998, 2025). "The influence of hyperglycemia on BAP1 expression in the UM_f81 and UM_m60 cells could not be analyzed because of insufficient cellular material." (PMID 41328998, 2025).
Hypoglycemia (1 paper, 2026). A decreased concentration of glucose in the blood. "Metabolic regulations by BAP1 were also reported in vivo using the neutron-encoded (NeuCode) amino acid labeling method, which observed hypoglycemia and metabolic alterations in various tissues of Bap1-knockout mice." (PMID 41602827, 2026).
liver fibrosis (1 paper, 2024). "Adhesion-related intestinal obstructions and liver fibrosis were seen in both WT and Bap1+/− mice, irrespective of whether they developed MM." (PMID 38592450, 2024).
low grade glioma (1 paper, 2023). A grade I or grade II glioma arising from the central nervous system. "Only PTEN in low-grade glioma and BAP1 in pan-kidney cohorts were prognostic across all three molecular features for either survival endpoint." (PMID 36950380, 2023).
lung diseases (1 paper, 2016). "To investigate the potential role of BAP1 in the generation and progression of LAC, we performed immunohistochemical staining on samples from 112 cases of LAC and 101 cases of non-neoplastic lung diseases." (PMID 27553041, 2016).
lymph node metastasis (1 paper, 2019). "Strong BAP1 staining was associated with adverse tumor features, including advanced tumor stage, high Gleason grade, presence of lymph node metastasis (p<0.0001 each) and a positive surgical margin (p=0.0019)." (PMID 31903168, 2019). "Strong BAP1 staining was associated with advanced tumor stage (p<0.0001), high classical and quantitative Gleason grade (p<0.0001), lymph node metastasis (p<0.0001), a positive surgical margin (p=0.0019) and early biochemical recurrence (p<0.0001)." (PMID 31903168, 2019).
lymphangioma (1 paper, 2019). A benign lesion composed of dilated lymphatic channels. "Studies have shown that MCPM biopsies are positive for a series of markers such as the proliferative protein Ki-67, cytokeratin 5/6, calretinin, BAP1, the transcription factor WT-1, and negative for endothelial markers (CD 31, CD 34, and factor VIII) whereas the opposite is true for lymphangioma." (PMID 31667333, 2019).
Lymphatic Metastasis (1 paper, 2018). Transfer of a neoplasm from its primary site to lymph nodes or to distant parts of the body by way of the lymphatic system. "Therefore, we analyzed another 12 independent ICC samples with (n = 6) or without lymphatic metastasis (n = 6), and found that BAP1 mRNA and protein expression were even lower in ICC with lymphatic metastasis than in those without lymphatic metastasis." (PMID 30305612, 2018).
mesenchymal neoplasms (1 paper, 2023). "After exclusion of reactive processes, carcinomas, and mesenchymal neoplasms, additional EMA, desmin, IMP‐3, and thrombomodulin positivity can be observed in the majority of cases, alongside with BAP1 loss." (PMID 36808895, 2023).
metastatic melanoma (1 paper, 2025). A melanoma that has spread from its primary site to another anatomic site. "Positivity for BAP1 is observed in an overwhelming majority of metastatic melanoma cases, with some studies reporting a figure as high as 95%." (PMID 40843873, 2025).
metastatic squamous cell carcinoma (1 paper, 2021). A squamous cell carcinoma which has spread from its original site of growth to another anatomic site. "BAP1-positive/claudin-4-negative expression was observed almost only in MPM with epithelioid features, while a single case of BAP1/claudin-4 negative metastatic squamous cell carcinoma from the anal region was observed." (PMID 34070888, 2021).
microsporidia infection (1 paper, 2026). "On the other hand, while USP16 levels remained stable, we observed a marked downregulation of both mRNA and protein levels of the BAP1 in response to EnP1 expression and microsporidia infection." (PMID 41499632, 2026). "Furthermore, we demonstrate that both EnP1 overexpression and microsporidia infection induce monoubiquitination of H2A (H2Aub) through downregulation of BAP1 expression." (PMID 41499632, 2026).
mucoepidermoid carcinoma (1 paper, 2022). A carcinoma morphologically characterized the presence of cuboidal mucous cells, goblet-like mucous cells, squamoid cells, cystic changes, and a fibrotic stromal formation. "Loss of expression of BAP1 was associated with a BAP1 mutation in one of the thymic mucoepidermoid carcinomas in which NGS testing was available." (PMID 35565429, 2022). "The mucoepidermoid carcinoma harbored a BAP1 Q40 and a PPP2R1A R260C mutation." (PMID 35565429, 2022).
muscular atrophy (1 paper, 2022). The loss of muscle tissue due to inactivity or disease. "Hence, we concluded that ablation of Bap1 in FAPs results in NMJ dysfunction, which then leads to severe muscular atrophy in Bap1ΔMPC mice." (PMID 35603786, 2022).
osteopetrosis (1 paper, 2023). Osteopetrosis, also known as marble bone disease, is a descriptive term that refers to a group of rare, heritable disorders of the skeleton characterized by increased bone density on radiographs. "Such being the case, we asked if Bap1 elimination only in mature osteoclasts similarly induces osteopetrosis." (PMID 37740028, 2023).
pericardial effusion (1 paper, 2022). Fluid collection within the pericardial sac, usually due to inflammation. "Immunohistopathological staining investigations, especially BRCA1‐associated protein 1 (BAP1) immunostaining using cell block sections of pericardial effusion, are effective in making a diagnosis of MPM." (PMID 35950141, 2022). "We should lower the threshold for BAP1 immunostaining in cases of recurrent pericardial effusion for an early diagnosis of MPM." (PMID 35950141, 2022).
peritoneal (1 paper, 2025). "Advances in molecular pathology, particularly the identification of BRCA1-associated protein 1 (BAP1) loss, have enhanced diagnostic precision and helped distinguish MPM from other peritoneal malignancies." (PMID 41147025, 2025).
pregnancy disorder (1 paper, 2021). A disorder that is related to pregnancy. "Gaining detailed insights into the molecular networks regulating this BAP1-ASXL modulation during early placentation will help not only to shed light onto the major unexplained pregnancy disorders, but also to open up new avenues into investigations of tumours where PR-DUB is mutated." (PMID 34170818, 2021).
prostate (1 paper, 2020). "Transwell migration assays showedthat BAP1-knockdown also inhibited the migration ability of prostate cancercells." (PMID 32422649, 2020).
rectal cancer (1 paper, 2025). A primary or metastatic malignant neoplasm that affects the rectum. "For example, BAP1 (BRCA-1 associated protein 1) appears to play a critical role in colonic carcinogenesis but not in rectal cancer." (PMID 40142201, 2025).
renal dysfunction (1 paper, 2025). "While not statistically significant, this finding corresponds with our previous work demonstrating lower rates of BAP1 mutations in RCC from patients with advanced CKD relative to patients without significant renal dysfunction." (PMID 40510153, 2025).
rhabdoid tumor (1 paper, 2025). An aggressive malignant embryonal neoplasm usually occurring during childhood. "Notably, BAP1 loss is more frequently observed in sarcomatoid and rhabdoid tumors, subtypes known to respond better to immunotherapy." (PMID 41561288, 2025).
skull-base tumor (1 paper, 2025). "The three cases presented illustrate distinct metastatic trajectories: long-latency spread from a recurrent, BAP1-altered tumor; rapid dissemination from an anaplastic (WHO grade 3) lesion; and progression in a multiply operated skull-base tumor complicated by treatment morbidity." (PMID 41552249, 2025).
small cell carcinoma (1 paper, 2022). A neuroendocrine carcinoma composed of small malignant cells which are often said to resemble "oat cells" under the microscope. "The small cell carcinoma did not harbor any reportable mutations; BAP1 and mTAP expression were preserved in this tumor." (PMID 35565429, 2022).
triple-negative breast carcinoma (1 paper, 2025). An invasive breast carcinoma which is negative for expression of estrogen receptor (ER), progesterone receptor (PR), and human epidermal growth factor receptor 2 (HER2). "As an oncogenic epigenetic factor, BAP1 has been shown to facilitate tumor metastasis via stabilizing KLF5 in triple-negative breast cancer." (PMID 39817454, 2025).
virus infection (1 paper, 2021). "In this study, we confirmed that MF116383 limits virus infection, and carried out further bioinformatic and phylogenetic analyses to better characterize this important gene—which we renamed bee antiviral protein-1 (bap1)." (PMID 38468887, 2021).
Waardenburg syndrome (1 paper, 2026). A disorder characterized by varying degrees of deafness and minor defects in structures arising from neural crest, including pigmentation anomalies of eyes, hair, and skin. "Among the piebaldism and Waardenburg syndrome genes, SOX10 and BAP1 expression exhibited the highest correlation in all 3 datasets, while KIT and MITF levels also correlated with BAP1 levels, albeit weaker." (PMID 41480773, 2026).